MALAT1 (metastasis associated lung adenocarcinoma transcript 1)
Diseases named in the same sentence as MALAT1 in open-access papers (continued):
Sharing a sentence is not in itself a finding about the gene and the disease.
glioma (continued). "This newly discovered lncRNA MALAT1/miR-384/GOLM1 axis may provide new insights into the mechanisms of glioma metastasis, and lncRNA MALAT1 may be a promising target for future glioma therapy." (PMID 33029125, 2020). "There is accumulating evidence that MALAT1 is overexpressed in gliomas." (PMID 31479414, 2020). "It is reported that lncRNA MALAT-1 inactivates ERK/MAPK pathway to mediate tumor suppression in glioma cells and may promote the proliferation and metastasis of gallbladder cancer cells by activating the ERK/MAPK pathway." (PMID 32509569, 2020). "Additionally, MALAT1 promoted glioma growth in a xenograft mouse model through regulation of miR-129 and SOX2." (PMID 32650527, 2020). "Although not all the aspects of MALAT1 derived from EVs in tumor inflammation have been deciphered, MALAT1 derived from GSC EVs could represent a specific target to treat glioma." (PMID 32117213, 2019). "For example, MALAT1 promotes FBXW7 expression by acting as ceRNA for miR-155 in glioma cells." (PMID 31248165, 2019). "MALAT1 also promotes FBXW7 expression by acting as a sponge of miR-155 in glioma cells." (PMID 31248165, 2019). "Considering miR-199a’s role in the carcinogenesis of glioma and its potential regulatory effect on ZHX1, we conducted a bioinformatics analysis, which predicted a binding interaction between miR-199a and MALAT1 (metastasis-associated lung adenocarcinoma transcript-1), a lncRNA." (PMID 31648104, 2019). "Through CCK‐8 proliferation assay, EdU assay and sphere formation assay, we also found that MALAT1 could promote the proliferation of glioma stem cells." (PMID 29808528, 2018). "Additionally, by sponging miR-101, MALAT1 abolished miR-101-dependent negative regulation of the autophagic program in glioma cells, thus prompting cell proliferation." (PMID 29739426, 2018). "Additionally, MALAT1 expression was increased in glioma tissues compared with that in adjacent normal tissues." (PMID 30266744, 2018). "Meanwhile, the percentage of EdU positive cells in si‐MALAT1 group also dramatically declined, suggesting that knockdown of MALAT1 could significantly repress the proliferation of glioma stem cells (both P < .01)." (PMID 29808528, 2018). "The results also indicated that the adverse prognostic effect of MALAT1 over-expression was obtained in different types of cancer (estrogen-dependent cancer: pooled HR = 2.656; urological cancer: pooled HR = 1.952; glioma: pooled HR = 2.315; digestive cancer: pooled HR = 2.451)." (PMID 30093838, 2018). "The decrease of MALAT1 expression suppressed the growth rate of glioma cells and induced apoptosis." (PMID 30583549, 2018). "Based on the data, the expression of MALAT1 is down-regulated in glioma tissue and cell lines." (PMID 30583549, 2018). "Besides, we would investigate the effect of MALAT1 on the proliferation of glioma stem cells and glioma tumorigenesis." (PMID 29808528, 2018). "This study hypothesized the promoter role of lnc MALAT1 in glioma and validated its effect in both in vivo and in vitro experiments." (PMID 29808528, 2018). "However, in patients with Alzheimer’s Disease or glioma, the cerebrospinal fluid and the tumor itself, respectively, showed MALAT1 upregulation." (PMID 29695738, 2018). "MALAT1 knockdown inhibited glioma stem cell proliferation via miR‐129 enhancement." (PMID 29808528, 2018). "For example, the lncRNA MALAT1 plays an important role in the progression and therapy of glioma and it may be considered an effective prognostic biomarker for the treatment of glioma." (PMID 29986541, 2018). "For the recent decade, increasing studies have demonstrated the influence of MALAT1 expression on clinicopathological parameters and prognostic outcomes among diffident types of cancer, including digestive cancers, gliomas, estrogen-dependent cancers, urological cancers and other cancers." (PMID 30093838, 2018).
glioma (continued). "High-throughput transcriptome analyses of glioma tissues/cells identified numerous highly and/or differentially expressed lncRNAs, including MALAT1, HOXA11-AS, and CRNDE, which correlate with histological and molecular subclassification, and/or show prognostic values." (PMID 30116729, 2018). "Ma et al11 revealed that MALAT1 was correlated with the malignant status in glioma." (PMID 29808528, 2018). "The present study showed that lncRNA MALAT1 has a tumor-suppressive function in glioma via suppressing both growth and invasion of cells, which is consistent with its lower expression levels in gliomas compared with normal brain tissues." (PMID 26938295, 2016). "Interestingly, subsequent research has demonstrated that HuR is necessary for the METTL3-mediated stabilisation of metastasis-associated lung adenocarcinoma transcript 1 (MALAT1), which in turn activates nuclear factor kappa B (NFB) in isocitrate dehydrogenase (IDH) wildtype glioma." (PMID 37444417, 2023). "In addition, MALAT1 expression was correlated with glioma tumor volume." (PMID 35071748, 2022). "Therefore, knockdown of MALAT1 promotes cell proliferation and invasion in glioma." (PMID 33980320, 2021). "In addition to SOX-2, MALAT1 downregulation has shown inhibitory effects on the expression of Nestin (another stemness marker) and proliferation of glioma stem cell lines by activating the ERK/MAPK signaling pathway, which is a key pathway in tumor development." (PMID 34322395, 2021). "Another lncRNA metastasis-associated lung adenocarcinoma transcript 1 (MALAT1) inhibits cell proliferation and invasion through the downregulation of extracellular signal-regulated kinase (ERK), matrix metalloproteinase 2 (MMP2) and MMP9 in U87 and U251 glioma cells and glioma nude mice models." (PMID 34202078, 2021). "Besides, GOLM1, a downstream target of miR-384, was also identified to promote autophagy by activating protein kinase AKT, suggesting that lncRNA MALAT1, as a miR-384 sponge, promoted vesicle nucleation and thus enhanced glioma migration and invasion by upregulating GOLM1." (PMID 33029125, 2020). "For example, MALAT1 could bind to other miRNAs in glioma stem cells." (PMID 29808528, 2018). "The controversy regarding the expression pattern of lncRNA MALAT1 in gliomas may be associated with the complexity of non-coding RNA biology and the heterogeneity of glioma tumors." (PMID 30583549, 2018). "However, a few other studies indicated MALAT1 has prooncogenic (tumor-promoting) roles and knockdown MALAT1 might confer beneficiary effects on glioma treatment." (PMID 30116729, 2018). "Besides, high levels of MALAT1 correlate with better overall survival of patients with glioma." (PMID 30583549, 2018). "Interestingly, preliminary reports showed that MALAT1 acted as tumor-suppressor gene, thus suggesting that its restoration might be a novel therapeutic approach against glioma." (PMID 29739426, 2018). "Thus, MALAT1 could be either a positive or a negative regulator in glioma tumorigenesis depending on cellular contexts." (PMID 30116729, 2018). "Furthermore, MALAT1-mediated tumor suppression in glioma cells may be via reduction of extracellular signal-regulated kinase/mitogen-activated protein kinase (ERK/MAPK) signaling activity and expression of matrix metalloproteinase 2 (MMP2)." (PMID 26938295, 2016). "After analyzing the existing literature, we can state that the most reliable data seem to be related to the action of certain lncRNAs in gliomas, such as HOTAIR, NEAT1, MEG3, and MALAT1." (PMID 41149459, 2025). "METTL3 also enhances MALAT1 stability through its interaction with RNA-binding protein HuR, leading to NF-κB activation and promoting IDH wild-type glioma progression." (PMID 41390674, 2025). "In glioma development, the involvement of HUR in METTL3-mediated m6A modification of the lncRNA MALAT1 has been observed, leading to increased MALAT1 transcript expression and the promotion of glioma development through the ERK/MARK pathway." (PMID 38649363, 2024).
glioma (continued). "In glioma, increased TMZ resistance, conferred by the upregulations of risky lncRNAs such as H19, MALAT1, PVT1, and SBF2-AS1, is likely to play a key role in the therapeutic efficacy of surgical resection plus drug treatment." (PMID 36819921, 2023). "This review compiles several differentially expressed lncRNAs in IDH-mutant and IDH-wildtype gliomas, and it has been shown that lncRNAs SBF2-AS1, PVT1, MALAT1, and H19 significantly contribute to the induction of TMZ resistance." (PMID 36819921, 2023). "For example, MALAT1, HOTAIR, and H19 have been found to promote glioma cell proliferation, migration, invasion, and angiogenesis, thereby acting as oncogenes." (PMID 37444408, 2023). "Among them, the expressions of MALAT1, LINC01018, and MEG3 were lower in glioma, and the three were discovered to be the lncRNAs that possibly targeted miR‐942‐5p." (PMID 36550594, 2023). "The dysregulated ceRNAs also contained 17 long noncoding RNAs (lncRNAs), such as MALAT1 and MIR22HG, which had been proved to play important roles in glioma." (PMID 35496054, 2022). "Hence, MALAT1 might be a potential therapeutic target for glioma." (PMID 35928868, 2022). "The expression of lncRNAs such as H19, HOXA11-AS, MALAT1, and CRNDE are positively correlated with glioma." (PMID 35372082, 2022). "For example, lncRNA MALAT1/miR-199a/ZHX1 axis suppresses glioblastoma proliferation and progression, and lncRNA-DLEU2/miR-186-5p/PDK3 axis advances glioma cell progression." (PMID 34459789, 2021). "MALAT1, NEAT1, and H19 are among lncRNAs that affect the response of glioma/glioblastoma to chemotherapy." (PMID 34178658, 2021). "MALAT1 promoted the level of ZHX1 by serving as a ceRNA of miR-199a, leading to augmented glioma development." (PMID 34178684, 2021). "Malat1 induces autophagy and promotes cell proliferation by sponging miR-101 and upregulating STMN1, RAB5A, and ATG4D expression in glioma." (PMID 34204169, 2021). "Accordingly, MALAT1 expression enhanced tumor proliferation by upregulating Rap1b and zinc-fingers and homeoboxes 1 (ZHX1) by sponging miR-101 in glioma and miR-199a in glioblastoma, respectively." (PMID 34322395, 2021). "Blood tumor barrier (BTB): MALAT1 knockdown led to enhanced BTB permeability and reduced expression of tight junction proteins in glioma endothelial cells via upregulating miR-140." (PMID 34322395, 2021). "Many lncRNAs had been elaborately discussed in this chemoresistance in glioma, such as LINC01198, SNHG15, and MALAT1." (PMID 33817241, 2020). "We analyzed the expression of the MALAT1/miR-199a/ZHX1 axis and its correlation with patients’ overall survival using two different glioma gene-expression datasets." (PMID 31648104, 2019). "H19 targets miR-15b in HCC, MALAT1 targets miR-1 in breast cancer cells, and SNHG15 binds to miR-153 in glioma vascular endothelial cells." (PMID 31248165, 2019). "Our study highlights the role of EV MALAT1-miR-129-5p-HMGB1 in the modulation of the inflammatory response in microglial cells, which holds great promise to serve as a therapeutic target for glioma treatments." (PMID 32117213, 2019). "However, the molecular mechanism of MALAT1 in glioma cells remains unknown." (PMID 29808528, 2018). "Emerging evidences have indicated that lncRNAs are correlated with glioma drug resistance, such as XIST, MALAT1, CACSC2, and H19." (PMID 29552296, 2018). "MALAT1 promotes cell proliferation by sponging miR-101 and increases cell resistance to temozolomide (TMZ) by regulating ZEB1 in glioma." (PMID 29552296, 2018). "Glioma stem cell lines of U87, SHG44 and SHG139 expressed higher levels of MALAT1 than their parental lines." (PMID 26938295, 2016). "The expressions of H19, MALAT1 and POU3F3, for instance, were positively correlated with more malignant glioma phenotypes, and H19 also modulates glioma cell invasion." (PMID 26230711, 2015).
glioma (continued). "Cancer proliferation and invasion genes were downregulated, including proliferation marker gene MKI67 with prognostic value in glioma, nerve growth factor receptor NGFR involved in GBM invasion, and long non-coding RNA MALAT1 with tumor suppressive function in GBM." (PMID 38177502, 2024). "Additionally, the knockdown of MALAT1 resulted in the downregulation of ATG4D, STMN1, and RAB5A expression in glioma cell lines." (PMID 36899946, 2023). "In addition, MALAT1 downregulates miR-101, consequently increasing resistance to TMZ in glioma cells by increasing glycogen synthase kinase 3β (GSK-3β) levels." (PMID 36819921, 2023). "Compared with regular (non-stem) glioma cells, GSCs showed higher levels of MALAT1, but lower levels of miR-129." (PMID 36321132, 2022). "In conclusion, this study revealed a new MALAT1/mir-124/ZEB2 axis that was correlated with glioma progression and could be a new therapeutic target in glioma." (PMID 35071748, 2022). "Studies showed that MALAT1 inhibited cell apoptosis and increased cell growth and activated autophagy via targeting miR-101 and derepressing Rap1B, RAB5A, ATG4D and STMN1 expression in glioma." (PMID 35928868, 2022). "Studies have shown that some lncRNAs such as HOTAIRM1 and colon cancer-associated transcript 2 (CCAT2), associated with tumorigenesis and cancer development, were upregulated in glioma, while other lncRNAs showing tumor-suppressive functions, such as RP11-838N2.4 and MALAT1, were downregulated." (PMID 34202078, 2021). "Prognostic value: Meta-analyses showed that increased MALAT1 expression could predict poor overall survival and higher “tumor, node, metastasis” (TNM) stage in glioma patients." (PMID 34322395, 2021). "For example, MALAT1 could activate autophagy by sponging miR-101 and upregulating STMN1, RAB5A, and ATG4D expressions in the glioma and, also, modulate the autophagy of retinoblastoma cell through miR-124-mediated stx17 regulation." (PMID 33450825, 2021). "All of these suggest that MALAT1 dependent EV-mediated microglia stimulation and IL-6, IL-8, and TNF-α secretion could contribute to glioma progression." (PMID 32117213, 2019). "In addition, MALAT1 activated autophagy and promoted cell proliferation by sponging miR-101 and up-regulating STMN1, RAB5A and ATG4D expression in glioma cells." (PMID 30266744, 2018). "H19, MALAT1 and HOXA11-AS down-regulates the expression of miR-140-5p in glioma." (PMID 30583549, 2018). "Silencing of MALAT1 suppressed the proliferation and stemness of GSCs and in vivo tumour growth via up‐regulating miR‐129 and further inhibiting SOX2, providing a promising therapy target for the treatment of glioma." (PMID 29808528, 2018). "Up-regulation of the lncRNA MALAT1 has been reported to correlate with tumor progression and poor prognosis in RCC, while some lncRNAs have been reported in other tumors, such as HOXA11-AS, which was regarded as a biomarker of poor progression in glioma." (PMID 30038853, 2018). "MALAT-1 knockdown significantly reduced MAPK/ERK signalling in gallbladder cancer cells, and when functioning as a tumour suppressor in glioma MALAT-1 in glioma acts by attenuating ERK/MAPK mediated signalling." (PMID 28430163, 2017). "MALAT1 can act as a transcriptional regulator of genes involved in cell cycle and cell migration, whilst ST7-AS1 does not have ontologies described, but has been associated with glioma." (PMID 37511270, 2023). "Both higher and lower MALAT1 expression are found in glioma than non-neoplastic tissue." (PMID 34322395, 2021). "However, MALAT1 also plays tumor-suppressive roles that involve repression of miR-155 and enhancement of F-box and WD repeat domain-containing 7 (FBXW7) function, which downregulates the expression of numerous oncoproteins in glioma cells." (PMID 33980320, 2021).
glioma (continued). "MALAT1 promotes the expression of sex determining region Y-box 2 (SOX2), thus boosting the viability and proliferation of glioblastoma stem cells, and it also suppresses apoptosis of glioma cells through reduction of Ras-related protein Rap-1b (Rap1B) levels by removal of miR-101." (PMID 32650527, 2020). "Another study reported that MALAT1 upregulated FBXW7 expression by modulation of the MALAT1-miR-155 pathway, which might serve as a novel prognostic biomarker and therapeutic target for glioma." (PMID 28977880, 2017). "Data showed that the expression of MALAT1 in noncancerous brain tissues was higher than in human brain glioma tissues (P<0.01), but there was no obvious difference between different degrees of malignancy in glioma (low-grade versus high-grade gliomas)." (PMID 26938295, 2016). "For example, MALAT1 knockdown increased the permeability of the blood‐tumor barrier, which might help to improve tumor penetration with therapeutics, while restoration of CASC2 expression upregulated PTEN and increased glioma sensitivity to TMZ‐based chemotherapy." (PMID 34316694, 2021). "For example, knockdown of MALAT1 increases permeability of the blood‐tumour barrier, which might contribute to the improvement of therapeutic strategies, while restoration of CASC2 expression up‐regulates PTEN and can increase glioma sensitivity to temozolomide‐based chemotherapy." (PMID 30117678, 2018). "However, MALAT1 had little effect on the expression of TIMP3 (data not shown), further indicating that the mechanism of MALAT1-suppressed glioma cell invasion is via downregulation of expression of MMP2 at the protein level." (PMID 26938295, 2016).